IL1B (interleukin 1 beta)
Diseases named in the same sentence as IL1B in open-access papers (continued):
Sharing a sentence is not in itself a finding about the gene and the disease.
gout (continued). "Chlorogenic acid has been shown to exert anti-gout activity as well as improvement on hyperuricemia and inflammation by inhibiting the XOD activity, serum UA levels, and production of proinflammatory cytokines (e.g. IL-1β and IL-6)." (PMID 30621705, 2019). "The potential anti-gouty arthritis effect of QZTB may be attributed to the inhibition of NLRP3 inflammasome and downstream proinflammatory cytokines (IL-1β and TNF-α) levels." (PMID 31885675, 2019). "Moreover, studies have confirmed that elevated levels of IL-1β and TNF-α can be detected in the blood of rats with gout and those of the hyperuricemia model." (PMID 30410553, 2018). "During attacks of gouty arthritis, MSU crystals induce mass leukocyte infiltration into the joint cavity and are phagocytosed by monocytes/macrophages, resulting in membranolysis and inflammasome activation, which releases interleukin (IL)-1β." (PMID 28874151, 2017). "On that basis, we hypothesized that procyanidins, a safe and effective natural product, might attenuate gout pain by inhibiting NLRP3 inflammasome activation and IL-1β maturation in macrophages." (PMID 28376889, 2017). "Appreciation of the centrality of IL-1β to gouty inflammation has led to the off-label use of anti-IL-1β therapies for patients who do not adequately respond to or cannot tolerate traditional gout medications." (PMID 28357052, 2017). "Notably, after stimulation with LPS, substantial amounts of IL-1β, IL-8, and TNF-α were detected in patients with gout." (PMID 29056937, 2017). "Based on the anti-inflammatory action of berberine, the study is to investigate the effects of berberine on NLRP3 and IL-1β in THP-1 cells with MSU crystals-induced inflammation on the basis of our previous research and to provide evidence for its application in gouty arthritis." (PMID 27689075, 2016). "Although the involvement of TLRs, NLRP3 inflammasome, and IL-1β in the MSU-induced inflammatory reaction is well-known, there are no miRNAs discovered, thus far, directly targeting TLRs, IL-1β, chemokines, and NLRP3 in gout." (PMID 27845712, 2016). "Extracellular TNF-α secretion was significantly reduced by the knockdown assays of endogenous ALPK1 and myosin IIA but not IL-1β thus IL-1β was not followed through into the human assays of gout patients." (PMID 27169898, 2016). "They suggest that synovial fibroblasts may participate in the secretion of IL-1β via NLRP3 inflammasome formation, which could make synovial fibroblasts a potential therapeutic target for gout." (PMID 25897296, 2015). "In a study among OA subjects without clinical gout, we recently demonstrated a strong positive association between synovial fluid uric level, IL18 and IL1β and OA severity as measured by imaging." (PMID 25925674, 2015). "We conclude that RPP15 may be a promising candidate for the development of a new treatment for gout and its activity of antigout may be partially related to inhibiting TNF-α, IL-1β, IL-8, and NF-κB p65 expression in the synovial tissues." (PMID 26221174, 2015). "In fact, it was shown that IL-1β mediates inflammation and dysfunction of the joint induced by the injection of monosodium urate (MSU) crystals into the knee in an experimental model of gout." (PMID 26330334, 2015). "Targeting IL-1β, e.g. through the use of Anakinra (a recombinant non-glycosylated version of human IL-1Ra) is already in use for the clinical treatment of gout and other IL-1β-related autoimmune diseases." (PMID 25497724, 2014). "mRNA transcripts of IL-1β in the PBMCs of gout patients did not have any difference after addition of MSU crystals to FFA C18:0, compared with healthy donors." (PMID 22762240, 2012). "Particularly, it is well accepted that gouty arthritis is primarily driven by TNF-α and IL-1β." (PMID 23304232, 2012).
gout (continued). "We found that production of IL-1β did not significantly differ between patients and controls, although IL-1β production in cells of gout patients showed a wide variation and a tendency to higher production when exposed to Pam3Cys." (PMID 22762240, 2012). "The in vitro studies performed until now have either studied human monocyte cell lines or primary mononuclear cells of healthy volunteers but the IL-1β production capacity of primary cells of patients with gout has not been investigated." (PMID 22762240, 2012). "This study also did not directly assess the relative contributions to chronic gouty arthritis of IL1α and IL1β, both of which are inhibited by rilonacept." (PMID 19635719, 2009). "In addition to glucose uptake, the hindrance of the tricarboxylic acid (TCA) cycle or the direct inhibition of immunoresponsive gene 1 may lead to a robust decrease in free radicals, M1-polarized macrophages, and IL-1β and TNF-α levels against gout." (PMID 39935474, 2025). "Furthermore, in the monosodium urate (MSU)-induced gout rat model, DTX effectively suppresses pro-inflammatory cytokines, including tumor necrosis factor-α (TNF-α), interleukin (IL)-1β, and IL-6 secretion, mitigating inflammatory damage and exhibiting anti-inflammatory properties." (PMID 39170709, 2024). "In patients with gout, the deposition and phagocytosis of monosodium urate crystals in tissues activate the NLRP3 inflammasome, leading to the production of critical cytokines such as IL-1β, IL-6, and tumor necrosis factor (TNF)-α, which are implicated in the occurrence of migraines." (PMID 38202145, 2023). "In a mouse model of gouty arthritis involving MSU injection into the ankle joint, this induced ankle oedema, mechanical allodynia, neutrophil infiltration, oxidative stress, NLRP3 inflammasome activation and increased production of the pro-inflammatory cytokines, IL-1β and TNFα." (PMID 37106238, 2023). "No studies using gevokizumab, another IL-1β inhibitor which may have potential to treat gout, were retrieved from our search, which is consistent with a 2018 report." (PMID 37491293, 2023). "After the involvement of the NLRP3 inflammasome in gout attacks was demonstrated, it was thought that only MSUc were responsible for the formation and activation of the NLRP3-ASC-caspase 1 protein complex, which performs proteolysis of pro-IL-1β to active IL-1β." (PMID 37996809, 2023). "Using these compounds, we studied whether SLC3031~3035 and SLC3037 at 5μM concentration could inhibit IL-1β release from bone marrow-derived macrophages (BMDMs) in response to MSU, an effector of inflammasome activation in gout in combination with LPS (LPS+MSU)." (PMID 38371945, 2023). "Our data showed that, in the process of gout disease, the expression of xanthine oxidase (XOD) has been increasing, which increases the level of uric acid, disrupts the balance of oxidative stress, generates a large amount of ROS, activates the NLRP3 inflammasome, and release IL-1β." (PMID 36569836, 2022). "The immune response during the development of hyperuricemia to gouty arthritis may be due to the increased expression of XOD, which promotes the production of uric acid, activates the release of ROS, and then activates the NLRP3 inflammasome and release IL-1β." (PMID 36569836, 2022). "Our data showed that, in the process of gout disease, the expression of XOD increases, which increases the level of uric acid in the body, disrupts the balance of oxidative stress, generates a large amount of ROS, activates the NLRP3 inflammasome, and release IL-1β." (PMID 36569836, 2022). "Some anti-inflammatory medications, like the IL-1β inhibitor canakinumab, may avoid gout episodes without changing serum urate concentrations." (PMID 36570535, 2022).
gout (continued). "However, in a gouty arthritis animal model, SMWE more efficiently downregulated MSU-crystal-induced swelling and pain, and it exerted anti-inflammatory effects by suppressing proinflammatory cytokines (IL-1β, TNF-α, and IL-6) and MPO activity." (PMID 33535406, 2021). "In particular, some cases of gouty arthritis were reported clinically, and only one experimental study reported that BV reduces levels of NF-κB nuclear translocation, leading to the suppression of proinflammatory cytokines such as TNF-α, IL-1β, and IL-6 in MSU-induced gouty mice." (PMID 34564665, 2021). "Therefore, cardamonin could reduce the level of NLRP3, caspase 1, IL-1β, and COX-2 under MSU stimulation, which might help for gout treatment." (PMID 34577821, 2021). "Also, the accumulation of acidic metabolites in the inflammatory environment inhibits the cAMP/PKA signaling pathway reducing the IL-1β production, which indirectly counteracts the purinergic signaling-mediated cAMP/PKA pathway activity, favoring gout resolution." (PMID 34925366, 2021). "The occurrence of MSU-mediated gout inflammation is a complex process, including the phagocytosis of autoimmune cells, the negative regulation of inflammatory mediators such as NLRP3 inflammasomes, Toll-like receptors and IL-1β, and the formation of aggregated neutrophil extracellular traps, etc." (PMID 33935726, 2021). "However, these experiments require the presence of LPS as a “priming signal” necessary for optimal IL-1β release, a component which is likely absent in gout patients." (PMID 32104502, 2020). "However, it remains unclear whether gallic acid can alleviate the inflammatory symptoms of gouty arthritis by inhibiting NLRP3 inflammasome activation and IL-1β expression." (PMID 33365024, 2020). "Current therapeutic strategies to target IL-1β have proven successful for alleviating the symptoms of gout in clinical studies, suggesting that targeting the NLRP3 inflammasome may have a critical impact on gout treatment." (PMID 31174271, 2019). "However, neither of these disease is primarily driven by IL-1β thus providing useful comparisons to gout." (PMID 30761138, 2019). "Nevertheless, these approaches were not effective in most gout patients and could not prevent joint damage since they target extracellular IL-1β after tissue damage has occurred." (PMID 31803174, 2019). "Synthesized the results of IL-1β and TNF-α changing tendency, it is indicated that knock out miR-146a discharged the repression of TRAK6 and IRAK1 function to accelerate the production pro-inflammatory cytokines and to exacerbate the MSU-induced gouty arthritis." (PMID 29544526, 2018). "However, unlike IL-1β blockade, there are no randomized clinical trials of tocilizumab in refractory gout." (PMID 30075804, 2018). "Therefore, the important targets for the management of inflammatory diseases, such as gouty arthritis include the reduction of swelling, pain, and inflammation by controlling the activation of inflammasomes, proinflammatory cytokines (TNF-α and IL-1β) and NF-κB." (PMID 28874151, 2017). "Some signatures of metabolome in male gout patients have been reported being involving in inflammation, such as acetate that regulates T cells, IL-8, TNF-α and 1L-1β through binding GPR43, succinate that induces IL-1β through HIF-1α and glucose that regulates T cell activation." (PMID 28270806, 2017). "Recent studies have suggested that IL-1β is a crucial inflammatory mediator induced by MSU crystals, indicating that IL-1β may serve as a potential therapeutic target for the treatment of acute gouty arthritis (GA)." (PMID 28915828, 2017). "Collectively, our results suggest that the inflammatory and gouty arthritis inhibitory effects of MPE primarily occur via the down-regulation of edema, pain and inflammation through the control of inflammasomes, proinflammatory cytokines (TNF-α and IL-1β), and NF-κB." (PMID 28874151, 2017).
gout (continued). "However, in patients with gout, MSU crystals also mediate local and systemic inflammatory processes which can induce many inflammatory cytokines, including tumor necrosis factor α (TNF-α), interleukin-1β (IL-1β), interleukin-6, and interleukin-8." (PMID 25250773, 2014). "The protein concentrations of inflammatory cytokines (IL-1β, TNF-α, and IL-6) significantly increased after ATG7 overexpression in MSU-stimulated THP-1 macrophages, suggesting that ATG7 may be involved in the mechanism of gout recurrence by promoting the release of inflammatory cytokines." (PMID 41221017, 2025). "Thus, we asked whether the reduced inflammasome activation and IL-1β production observed in TRAF1 mutants that do not interact with cIAP2 could be beneficial in an inflammasome-driven disease like gout." (PMID 41285029, 2025). "Thus, when gout patients experienced an acute flare, it is unclear whether changes in urate excretion also involved URAT1 and GLUT9, and whether changes in those two modes of transport were mediated by IL-1β or other inflammatory factors." (PMID 36896178, 2023). "Moreover, catechins exhibit potent free radical scavenging activity, significantly reducing the secretion of IL-1β and IL-6 in C57BL/6 mice induced by MSU crystals, while inhibiting the activation of the NLRP3 inflammasome, thus effectively reducing the likelihood of developing gout in patients." (PMID 37519890, 2023). "In addition, LXA4 could significantly depress serum IL-1β and TNF-α in gouty arthritis rats." (PMID 36569930, 2022). "Thus, diminishing the production of IL-1β or TNF-α in macrophages by inhibiting the M1 polarization and/or NLRP3 inflammasome activation via the NF-κB signal pathway could be an effective strategy to treat gouty arthritis." (PMID 33505510, 2021). "Thus, we conclude that wedelolactone partially suppresses the production of MSU‐elevated IL‐1β and caspase‐1 (p20) in vivo, thereby limiting NLRP3 inflammasome activation and neutrophil influx, suggesting that wedelolactone may be a potential candidate in the treatment of gouty arthritis." (PMID 32656909, 2020). "Secondly, monocytes isolated from gout patients were more responsive to Pam3, but not to Pam3+MSU where the levels of IL-1β secreted were similar to those from healthy control monocytes." (PMID 30761138, 2019). "Besides reducing uric acid levels in gout treatment, febuxostat, but not allopurinol, prevents NLRP3 inflammasome assembly and blocks IL-1β production by macrophages." (PMID 40399065, 2025). "Furthermore, there were no statistical differences of tear IL‐1β and TNF‐α levels between asymptomatic hyperuricemia group and gout group, suggesting that ocular inflammation has been overexpressed during the asymptomatic hyperuricemia period." (PMID 36988248, 2023). "In a patient population with gout, IL-1β protein concentrations in serum were significantly higher compared to healthy controls, and patients with UAN had significantly more IL-1β than patients with gout but without renal damage." (PMID 35204131, 2022). "The current study identified that the use of ALP or ZUR alone failed to reduce levels of IL-1β and TNF-α in hyperuricemic mice, suggesting that the co-administration of ALP and ZUR exerted their anti-inflammatory effect to prevent development of gout from HU." (PMID 32041665, 2020). "MSU crystals alone failed to induce IL-1β, IL-6 or TNFα in both patients and control groups, but a stronger synergy between MSU/Pam3Cys and MSU/C18:0 for the induction of IL-1β was found in patients with gout compared to healthy controls." (PMID 22762240, 2012). "Interestingly, celastrol is reported to inhibit the activation of the NLRP3 inflammasome in LPS-induced liver damage and monosodium urate-induced gouty arthritis by blocking the de-ubiquitination of NLRP3 and cleavage of pro-IL-1β, without affecting the total protein level of NLRP3." (PMID 40391077, 2025).
gout (continued). "Our data demonstrated that increased IL-33 expression in gout patients might be a negative feedback mechanism on the MSU-induced inflammation response, because the inflammatory cytokine IL-1β production and the number of neutrophils were both markedly decreased in IL-33-treated mice." (PMID 30863362, 2019).
viral infection (475 papers, 2005 to 2026). "Zebrafish with Bcl3 deficiency further showed enhanced immune responses and increased susceptibility to both bacterial and viral infections, resulting in significantly elevated levels of pro-inflammatory cytokines il1b, il6, il8, and tnfa." (PMID 41439955, 2025). "The consequent decline in the release of IL-1β and IL-18 leads to a reduction in inflammation caused by viral infection." (PMID 40189592, 2025). "Previous studies have also demonstrated that PM2.5 increases susceptibility to bacterial and viral infections by altering levels of pro-inflammatory cytokines (e.g., IL-1β, IL-6, and IFN-β), thereby elevating the risk of frailty." (PMID 41404569, 2025). "When RVs overcome this defense line, type I IFNs come into play, leading to an inflammatory response essential for eradicating viral infections but also capable of causing tissue damage mediated by proinflammatory cytokines like IL-6 and IL-1β." (PMID 41301463, 2025). "CXCL10 and IL1B encoding proteins are the pro-inflammatory cytokines that are involved in a wide variety of processes, and thereby play an important role during viral infections by stimulating the activation and migration of immune cells to the infected sites." (PMID 39698468, 2024). "IL-1β production and secretion are essential components of inflammation of the innate immune response associated with viral infection." (PMID 35254168, 2022). "The placental inflammatory response, specifically IL‐1β, induced by viral infections, is known to increase the risk of perinatal developmental abnormalities." (PMID 35141964, 2022). "Among several inflammasomes, NLRP3 inflammasome is the best-characterized one and is linked to the maturation and release of IL-1β in viral infection." (PMID 33708197, 2021). "Especially, viral infection caused a tenfold increase of IL‐1β and IL‐6 level in the culture medium from the lower endothelium layer as compared to the group without infection." (PMID 33173719, 2021). "This demonstrates that there are still a lot of uncertainties associated with IL-1β and its role in viral infections and innate immune responses." (PMID 34696506, 2021). "IL-1β is a key member of the interleukin family, which modulates the inflammation caused by bacterial and viral infections." (PMID 32103450, 2020). "Treatment of the Supnt with both Abs further restored the susceptibility of MDMs to CCR5 HIV-1 Env-tropic virus infection, thus underlining the antiviral impact of IL-1β and TNF-α." (PMID 32994328, 2020). "This was further confirmed by western blot analysis showing that NLRP3 deficiency blocked the secretion of mature IL-1β and caspase-1 in supernatant of Park2−/− cells after viral infection." (PMID 31229895, 2019). "Upon exposure to bacterial or viral infection, osteoblasts can directly respond to pathogen-associated molecular patterns (PAMPs), such as LPS, with the release of several cytokines, including IL-1β, IL-6, and TNF-α." (PMID 31892163, 2019). "Virus infection caused significantly increased IL-1β and IL-6 as well as significantly decreased IL-10 in the control infected group (P < 0.01)." (PMID 31551774, 2019). "In the course of virus infection, IL-1β acts as a key pro-inflammatory factor causing excessive inflammatory response, which eventually leads to tissue damage and other diseases." (PMID 32047436, 2019). "Loss of epithelial integrity was accompanied by increased IL-1β expression in Paneth cells, suggesting a possible mechanism whereby Paneth cells respond to viral infection by secreting IL-1β, although the Paneth cells themselves were not infected." (PMID 29701691, 2018). "IL-1β, which is a key cytokine, is associated with both acute and chronic inflammation and with viral disease." (PMID 30013955, 2018).